MAN2B2 (mannosidase alpha class 2B member 2)
Description:
Specifically cleaves terminal alpha 1,6-linked mannose residues on Man3GlcNAc and Man2GlcNAc core oligosaccharides generated by N-glycan degradation pathways, having little activity, if any, on larger mannose oligosaccharides. Does not cleave terminal alpha 1,6-linked mannose on Man3GlcNAc2, and is also unable to hydrolyze terminal alpha 1,3-mannose linkages.
Synonyms: Epman; KIAA0935; CDG1EE
Tractability: Antibody: UniProt places it where antibodies can reach, with high confidence; UniProt predicts a signal peptide or a membrane-spanning region; its Gene Ontology location is reachable by antibodies, with medium confidence. PROTAC: ubiquitination databases record sites on it; its protein half-life has been measured.
Target class: Enzyme; Hydrolase
Gene: Protein-coding gene on chromosome 4 (6,575,174 to 6,623,362, forward strand). Ensembl gene ENSG00000013288.
Subcellular location: Secreted
Pathways (Reactome):
Metabolism: Lysosomal oligosaccharide catabolism
Gene Ontology:
Molecular function: alpha-mannosidase activity; mannan endo-1,6-alpha-mannosidase activity; mannosyl-oligosaccharide 1,6-alpha-mannosidase activity; protein binding; carbohydrate binding; mannosidase activity
Biological process: glycoprotein catabolic process; oligosaccharide catabolic process; carbohydrate metabolic process; mannose metabolic process
Cellular component: extracellular exosome; extracellular region; lysosomal lumen; lysosome
Genetic constraint (gnomAD): Loss-of-function variants: 104 observed, 119.69 expected, observed/expected ratio (o/e) 0.87, 90% interval 0.74 to 1.02. The upper end of that interval is the gene's LOEUF score, 1.02, which puts it in group 4 of 6, group 1 being the genes least tolerant of losing a copy. Missense variants: 1,313 observed, 1,408.7 expected, observed/expected ratio (o/e) 0.93, 90% interval 0.89 to 0.98. Synonymous variants: 541 observed, 606.04 expected, observed/expected ratio (o/e) 0.89, 90% interval 0.83 to 0.96.
Homologues: Orthologues: chimpanzee MAN2B2 (99% identical), macaque MAN2B2 (89% identical), mouse Man2b2 (76% identical), rat Mrfap1 (74% identical), pig MAN2B2 (68% identical), guinea pig MAN2B2 (67% identical), tropical clawed frog man2b2 (60% identical), zebrafish man2b2 (57% identical). Paralogues in human: MAN2B1 (27% identical), MAN2A2 (26% identical), MAN2A1 (26% identical), MAN2C1 (15% identical).
Diseases named in the same sentence as MAN2B2 in open-access papers:
MAN2B2 is named in the same sentence as 11 diseases in open-access papers, as found by Europe PMC text mining. Sharing a sentence is not in itself a finding about the gene and the disease. The quoted sentences say what the papers report.
immune deficiency (3 papers, 2021 to 2023). "The patient presented immune deficiency and severe developmental delay caused by a homozygous missense variant in the MAN2B2 gene." (PMID 35637269, 2023). "A novel pathogenic variant causing a combined immune deficiency, abnormal glycosylation, and lysosomal involvement was described as MAN2B2-CDG." (PMID 37858231, 2023). "The MAN2B2 gene involved with lysosomal degradation of glycoproteins, and in 2019 a physician diagnosed a patient with immune deficiency as a result of a loss of function mutation in the gene." (PMID 33595436, 2021). "To date, only one case of MAN2B2 deficiency had been reported to cause a new type of CDG with severe growth delay, intellectual or developmental disability and immune deficiency, and MAN2B2-CDG case with genital and skeletal anomalies has never been reported." (PMID 35637269, 2023). "Here we presented a case with compound heterozygous variants in the MAN2B2 gene, causing global developmental delay, cleft palate, and hypospadias but no immune deficiency." (PMID 35637269, 2023).
hepatocellular carcinoma (2 papers, 2020 to 2022). A malignant tumor that arises from hepatocytes. "Furthermore, studies have shown that the circRNA MAN2B2 promotes the proliferation of hepatoma cells through the miRNA-217/MAPK1 axis, which indirectly supports our results." (PMID 35844837, 2022).
Alzheimer disease (1 paper, 2025). A progressive, neurodegenerative disease characterized by loss of function and death of nerve cells in several areas of the brain leading to loss of cognitive function such as memory and language. "A few male Tyr DEGs were unchanged in level regardless of NAP treatment, including Tyr up-regulation of Pla2g4e, which is associated with cognitive resilience in late-onset Alzheimer’s disease models and down-regulation of the glycosylation-related Man2b2." (PMID 39715923, 2025).
cardiac hypertrophy (1 paper, 2023). "MAN2B2 has been reported as a potential early biomarker for cardiac hypertrophy and heart failure in an isoproterenol-induced model of cardiac hypertrophy in the mouse." (PMID 37277858, 2023).
developmental delay (1 paper, 2023). "Although our proband shared some features with the reported MAN2B2-CDG, such as developmental delay or intellectual disability, he showed a few different clinical manifestations from the reported one." (PMID 35637269, 2023).
Intellectual disability (1 paper, 2023). "Interestingly, the loss of function of three of the six human-biased glycan degradation genes (MANBA, MAN2B2, and MAN2B1) is associated with intellectual disability." (PMID 36658652, 2023).
MAN2B2 also shares sentences with these, for which no sentence is quoted: breast carcinoma (1 paper); cancer (1); Esophageal Carcinoma (1); heart failure (1); neoplasia (1).